LAG3 (lymphocyte activating 3)
Diseases named in the same sentence as LAG3 in open-access papers (continued):
Sharing a sentence is not in itself a finding about the gene and the disease.
tumor (continued). "Previous results using subcutaneous immunization with MVA-BN-HER2 against CT26.HER2 tumors indeed showed a slight increase of Lag3-positive cells in the tumor microenvironment 16 days after vaccination." (PMID 31695037, 2019). "Major differences in receptor expression were associated with activation (HLA-DR, CD69), tumor recognition (NCRs and NKp80), and immune regulation (TIM-3 and LAG-3)." (PMID 31695700, 2019). "Mice without STAT3 in myeloid compartment of tumor stroma, including DCs and macrophages, present reduced numbers of tumor-infiltrating CD4+CD25+/FOXP3+/LAG3+ Tregs, along with an increase in CD8+ effector T-cells." (PMID 31480382, 2019). "The possibility, however, that expression of PD-1 and LAG-3 on TILs, as well as on tumor cells in a minority of cases, represents an indicator of immune dysregulation is certainly of interest." (PMID 31007846, 2019). "The expression of inhibitory receptors (e.g., CTLA-4, PD-1, Lag-3) by tumour-infiltrating lymphocytes cells has gained significant attention in recent years in the oncology field." (PMID 30413828, 2019). "Kinetic studies revealed that the percentage of Nrp-1+ CD8+ TIL increased during tumour growth, with similar induction of PD-1, LAG-3 and Tim-3 and, to a lesser extent, CTLA-4." (PMID 31350404, 2019). "Both PD-1 and LAG-3 were positive on tumor cells in a minority of DLBCL cases (8.3% and 7.5%, respectively), but were more widely expressed on TILs in a correlated manner." (PMID 31007846, 2019). "Considering that we observed PD-1, TIM-3 and LAG-3 expression in TILs, and TIM-3 expression in tumor cells of many cases of DLBCL, we next investigated the effects of blocking PD-1, TIM-3 and LAG-3 in the context of tumor-specific cytotoxic activity." (PMID 31007846, 2019). "Studies in murine tumor models have demonstrated that blockade of lymphocyte-activation gene 3 (LAG-3) alone or in combination with PD-1 antibodies limits tumor growth and promotes clearance of malignant cells." (PMID 31332464, 2019). "The inhibitory receptors PD-1, Tim-3, and Lag-3 are highly expressed on tumor-infiltrating lymphocytes and compromise their antitumor activity." (PMID 31511513, 2019). "LAG-3 has been shown to be expressed in TILs of several tumor types, including breast, ovarian, and lung cancers, often in connection with increased PD-1+ T cells." (PMID 31007846, 2019). "Significantly alterations on the expression of tumor recognition (NCRs and NKp80), and immune regulation receptors (LAG-3, TIM-3, and CD137) by NKT-like cells were observed in CML patients." (PMID 31695700, 2019). "Other potential biomarkers that remain to be further investigated are the levels of TILs, primary site and metastatic site of tumour, tumour volume and downregulation or overexpression of other immune regulatory signals such as LAG3." (PMID 31607751, 2019). "Circulating human pDC are activated through LAG-3 in a TLR independent fashion with limited IFN-α and enhanced IL-6 production, confirming a similar phenotype to tumor-associated suppressive pDC." (PMID 30788290, 2019). "In HNSCC, the increased expression of LAG3 in TILs was related to higher pathological grades, larger tumor size and positive lymph node status." (PMID 31708918, 2019). "Dual genetic knockout of LAG-3 and PD-1 can delay tumor growth and enable mice to live markedly longer." (PMID 30603054, 2018). "Preclinical data suggest that dual LAG-3/PD-1 blockade synergistically reverses tumor-specific anergy." (PMID 30400822, 2018). "A role of dual blockade of LAG3 and PD-1 in tumor immunity is suggested by studies in which most tumors implanted in LAG3/PD-1 double-knockout mice were rejected, whereas PD-1 single-knockout mice showed delayed tumor growth." (PMID 29482595, 2018). "The tumor progression in wild-type samples was associated with upregulation of immunoinhibitory genes, including PD-1, CTLA-4, TIM3, and LAG3." (PMID 29296022, 2018).
tumor (continued). "We found that the distribution of both trimethyl histones in the promoter region of PD-1, CTLA-4, and LAG-3 was reduced in tumor compared with normal tissues." (PMID 29983831, 2018). "IMP321, a soluble form of LAG-3, upregulates co-stimulatory molecules and increases interleukin (IL)-12 production to enhance tumor immune responses." (PMID 29544515, 2018). "Further immunophenotypic analysis of PD-1+LAG-3+ T cells in tumor lesions of EBL animals is desired to be conducted to address this issue." (PMID 29914540, 2018). "Analysis of the phenotypical and functional evolution of CD8+ TILs from 32 patients with NSCLC revealed that the accumulative expression of PD-1, TIM3, CTLA-4, LAG-3, and BTLA on CD8+ T cells was associated with tumor stage and nodal status." (PMID 29482595, 2018). "LAG-3 regulates anti-tumor immune responses interestingly parallels to CTLA-4, a well-known cancer immune checkpoint." (PMID 30603054, 2018). "In case of LAG-3 promoter, both repressive histones bind weakly in tumor tissues compared to normal tissues." (PMID 29983831, 2018). "Poxvirus-based active immunotherapy with PD-1 and LAG-3 dual immune checkpoint inhibition overcomes compensatory immune regulation, yielding complete tumor regression in mice." (PMID 30400835, 2018). "It was shown that LAG-3 antibodies alone or in combination with PD-1 blockers curtailed growth of malignant cells and promoted tumor clearance." (PMID 30233564, 2018). "The second is antagonistic LAG-3 antibodies which release the brakes of the anti-tumor immune response, such as BMS-986016, LAG525, REGN3767and TSR-033." (PMID 30603054, 2018). "Specifically, LAG-3 has been shown to maintain tolerance to tumor antigens via its effects on CD8+ T cells." (PMID 30101129, 2018). "LAG-3 and PD-1 are frequently co-expressed and upregulated on tumor-infiltrating lymphocytes (TILs) leading to immune exhaustion and tumor growth." (PMID 29544515, 2018). "Galectin-3 is widely expressed in different cell types; thus interaction with LAG-3 serves to broaden LAG-3's immune regulatory impacts on tumor-infiltrating CD8+ T cells within the TME." (PMID 30603054, 2018). "In vivo, bispecific PD- 1/LAG-3 Nbs demonstrated notable anti tumor effects in multiple tumor models." (PMID 30400835, 2018). "A number of studies in murine tumor models have provided a rationale for LAG-3 blockade to limit tumor growth." (PMID 30233564, 2018). "Triple blockade of PD-1, TIM-3, and LAG3 resulted in highly effective reversal of T cell exhaustion and achieved improved tumor control over single or double combinations." (PMID 30400835, 2018). "Optimal enzymatic dissociation was essential for analysis of critical tumor-specific sub-populations, such as PD1hiTim3+Lag3+CD39+CD8+ T cells present in tumors." (PMID 30400835, 2018). "More PD-L1+ ICs, Tim-3+ ICs and LAG-3+ ICs were found in the CD8-rich tumor microenvironment, which is in accordance with the feedback nature of immune system." (PMID 30285868, 2018). "Persistent T-cell activation in a chronic inflammatory environment, such as in a tumor, results in sustained LAG3 expression, contributing to a state of exhaustion manifest in impaired proliferation and cytokine production." (PMID 30400822, 2018). "LAG-3 is another important inhibitory immune check point and exerts synergistic effects with PD-1/PD-L1 on T cell activation in the tumor microenvironment." (PMID 29843754, 2018). "Here, we explore the functional effects of triple blockade of PD-1, TIM-3, and LAG3 on T cell activation, tumor immune contexture, and antitumor activity in preclinical models." (PMID 30400835, 2018). "Tumor-infiltrating CD4+ T cells exhibit traits of chronic exhaustion during tumor progression, accompanied by up-regulation of inhibitory receptor LAG-3." (PMID 30603054, 2018).
tumor (continued). "Unexpectedly, IL-2/CD40 promoted a more regulatory phenotype in young tumor-associated CD8+ T cells, on account of increases in several regulatory markers, relative to PBS controls, specifically: CD39, A2AR, A2BR, ICOS, LAG-3, and PD-1." (PMID 30560130, 2018). "This study aims to quantitatively assess the content and spatial interaction of key immune suppression components (e.g. PD-1 & LAG3 for T cell exhaustion, PD-1/L1 interaction) in tumor micro- environment, and their predictive values to anti-PD-1 treatment." (PMID 30400822, 2018). "In three distinct transplantable tumor models, LAG-3 and PD-1 have been shown to be co-expressed on tumor-infiltrating lymphocytes, and blockade of both pathways had synergistic effects on the anti-tumor CD8+ T cell response." (PMID 29535740, 2018). "LAG3.NC-CD4Cre and LAG3.NC-ThPOKCreERT2 mice resist anti-PD1 therapy and succumb to MC38 tumor growth, compared to ~40% of controls and LAG3.NC-E8ICre.GFP mice becoming tumor-free." (PMID 30400822, 2018). "In many tumor samples from patients, sustained co-expression of LAG-3 and PD-1 can modulate T cells exhaustion state." (PMID 30603054, 2018). "We have successfully discovered a LAG3-blocking therapeutic antibody with high binding affinity and strong potency in the T cell re-invigoration and anti-tumor efficacy." (PMID 30400822, 2018). "The finding is strongly supported by the research in NSCLC patients, in which LAG-3 expression on tumor-infiltrating Tregs is elevated, compared to peripheral blood and normal adjacent tissues." (PMID 30603054, 2018). "In both groups of mice, OT-I cells up-regulated the activating receptor LAG3, and acquired central or effector memory phenotype, whereas OT-I cells maintained the naive phenotype of the harvest in tumor-free control mice." (PMID 30042420, 2018). "Specially, in the setting of advanced cancer, LAG-3 is preferentially expressed on tumor-infiltrating Tregs and these Tregs display a terminal effector phenotype and proliferate less than LAG3− Tregs." (PMID 29225597, 2017). "Simultaneous blockade of PD-1 and LAG-3 synergistically improved viral control and tumor eradication." (PMID 29255458, 2017). "Co-blockade of the LAG-3 and PD-1 pathways is more effective for anti-tumor immunity than blocking either molecule alone." (PMID 28545567, 2017). "Recent studies show that tumor-infiltrating Tregs can induce much higher expression of many immune checkpoint molecules such as LAG-3, TIM-3, GITR, CTLA-4 and PD-1, making them feasible targets for ICPI." (PMID 29312592, 2017). "Activated T cells in vitro induce MDSC function through IL-10; these MDSC secrete ARG-1 and IDO and express PD-L1 and MHC-II, leading to upregulation of PD-1 and LAG-3 on T-cells, promoting an immunosuppressive tumor microenvironment." (PMID 28970830, 2017). "LAG-3 expression was also increased in tumor infiltrating HBV-specific CD8+ T cells obtained from HCC patients, which correlated with severe functional defects at the tumor site." (PMID 28703774, 2017). "Co-expression of LAG-3 and PD-1 has been seen in tumor infiltrating lymphocytes (TILs) in tumor mouse models as well as human tissue, suggesting its role similar to PD-1." (PMID 28482851, 2017). "Loss of activity of human CAR-T cells against tumor cells in NSG mice or humans was associated with expression of multiple inhibitory receptors including PD-1, BTLA, LAG3, TIM3, and 2B4." (PMID 28239463, 2017). "In this regard, LAG-3 and PD-1 blockade together can induce almost complete tumor regression in mice with established MC38 or SA1N tumors, in contrast to only ~15% efficacy when only one of the two receptors is blocked." (PMID 28443090, 2017). "This role in activating DCs has been further demonstrated in mouse models, where LAG-3-Ig used as a vaccine adjuvant has been shown to improve the anti-tumor immune response." (PMID 29211042, 2017).
tumor (continued). "More recently, Foy and colleagues observed complete regression of CT26.HER-2 tumours combining immunotherapy with dual PD-1 and LAG-3 blockade." (PMID 28537896, 2017). "Six days following vaccination with MCMVgp100KGP, PMEL cells within the tumor microenvironment expressed high levels of the inhibitory receptors LAG3, PD-1, and NKG2A compared to PMEL cells in the blood." (PMID 29387061, 2017). "Taken together, the co-expression of LAG-3 with PD-1 and TIM-3 formed a defined population of PD-1+TIM-3+LAG-3+ T cells in the tumor microenvironment of FL." (PMID 28977875, 2017). "Pathogen-specific CD8+ T cells in mouse models and humans with chronic viral infections as well as TILs from mouse tumor models and patients with cancer can coexpress multiple repressors, including PD-1, LAG-3, TIM-3, TIGIT, and others." (PMID 28443090, 2017). "Blockade with a combination of anti-PD-L1 and anti-LAG-3 mAbs overcame the requirement to deplete tumor-specific Tregs in this model." (PMID 28970830, 2017). "Using tumor samples from 28 FL patients, we found that LAG-3+ T cells accounted for a median of 6.97% (range: 2.7%- 46.9%) of intratumoral CD3+ T cells and 8.11% (range: 3.02%-50.6%) of intratumoral PD-1+ T cells." (PMID 28977875, 2017). "Soluble LAG-3 has been commercially developed for further clinical testing given the promising pre-clinical findings and potential in augmenting the anti-tumor immune response." (PMID 29211042, 2017). "A few examples of those newly discovered molecules that are now being evaluated in preclinical tumor models and/or even in clinical trials are lymphocyte activation gene 3 (LAG3) protein and T cell immunoglobulin and mucin domain-containing 3 (TIM3) protein." (PMID 27151159, 2016). "The analysis of WASp KO NK cells implies that increased expression of KLRG1, LAG-3 and DNAM-1 was associated with normal tumor rejection capacity, at least when multiple ligands and cytokines such as IL-2 was produced by tumor cells." (PMID 27477778, 2016). "It was previously reported that the expression of LAG-3 in tumour-infiltrating CD8+ T cells was also limited to intracellular stores." (PMID 27198196, 2016). "Our data shows that patients with high expression levels of LAG3 in the tumor compartment presented a better outcome." (PMID 27463005, 2016). "Remarkably, in vitro results showed that the secreted anti-PD-L1 IgG1 or IgG4 can interact with the PD-L1+ RCC cells, reverse upregulation of the exhaustion markers PD-1, TIM-3 and LAG-3 and restore tumor cell killing." (PMID 27145284, 2016). "The cohort of 402 primary HNSCC tumor samples was evaluated for PD-L1 expression on TC and IC as well as for PD-1, LAG-3, and ICOS expression on IC." (PMID 27841362, 2016). "In contrast, anti-PD-1 monotherapy triggered significantly higher levels of LAG-3 expression than MVA-BN-HER2 therapy but T cells remained confined to the tumor periphery." (PMID 26910562, 2016). "Dual blockade of PD-1 and LAG-3 significantly inhibited the tumor growth of KRS-SCCs, suggesting a functional relevance of their co-expression on TILs." (PMID 27835902, 2016). "Anti-LAG-3 mAb treatment in solid tumor models has shown success in inhibiting primary tumor growth through activation of antigen-specific T-cells in the TME." (PMID 31093342, 2016). "The mismatch repair–deficient tumor microenvironment strongly expressed several immune checkpoint ligands, including PD-1, PD-L1, CTLA-4, LAG-3 and IDO, to protect the tumor cells from death." (PMID 26967246, 2016). "Prior studies have also shown a synergistic role of PD-1 and LAG-3 in suppressing T cell functions in the context of tumor immune evasion." (PMID 27835902, 2016). "Our data showed that dual blockade of PD-1 and LAG-3 significantly inhibited the tumor growth in the treated group compared to control one." (PMID 27835902, 2016).
tumor (continued). "Levels of LAG-3 and PD-1 were significantly higher on T cells present in the tumor microenvironment, compared to circulating cells of the same patients." (PMID 26700461, 2016). "Collectively, these data indicate that myeloid suppressive cells consistent with the phenotype of MDSCs are present in tumor metastases, along with TILs expressing PD-1 and LAG-3 markers." (PMID 26700461, 2016). "It is possible that blockade of Lag-3 led to decreased suppression within the tumor that resulted in delayed tumor growth in the MC-38 model." (PMID 27050669, 2016). "LAG-3 has been identified as a key regulatory molecule involved in prevention of autoimmune disease, as well as the development of tumor tolerance." (PMID 31093342, 2016). "LAG3 expression is upregulated on TILs and blockade of LAG3 can enhance anti-tumour T cell responses." (PMID 27050669, 2016). "Beyond the PD-1/PD-L1 axis of immune suppression pathways, LAG-3 expression has also been shown to impact T cell mediated anti-tumor immune responses." (PMID 26910562, 2016). "Our results showed that both CD8+ and CD4+ TILs co-expressed inhibitory receptors, PD-1 and LAG-3, and dual blockade of PD-1 and LAG-3 significantly suppressed the tumor growth of SCCs." (PMID 27835902, 2016). "Combining MVA-BN-HER2 immunotherapy with dual PD-1 plus LAG-3 blockade resulted in comprehensive tumor regression in all mice treated with the triple combination therapy." (PMID 26910562, 2016). "The association of LAG3 and PD1 also occurred in OT-1 CD8+ T cells that were re-stimulated with antigen (OVA)-expressing tumor cells (IE9mp1) (lane 1 and 2)." (PMID 26318293, 2015). "Experiments suggest a synergistic interaction between combination anti-PD-1 and anti-LAG3 therapies that appears to enhance anti-tumor immunity, in part by preventing exhaustion and anergy in effector T cell populations." (PMID 25763356, 2015). "Gal-3 binds to LAG-3, and LAG-3 expression is necessary for Gal-3-mediated suppression of tumor-specific CD8 T cells." (PMID 26347741, 2015). "Combinations of anti-LAG-3 antibodies with anti PD-1 antibodies showed decreased tumor growth and enhanced antitumor immunity, and also maintained immune homeostasis with decreased autoimmune responses." (PMID 26487966, 2015). "LAG-3 and PD-1 are co-expressed on TILs in ovarian and on tumor-specific CD8 T cells in the blood of ovarian cancer patients." (PMID 26347741, 2015). "The expression of PD-1, CTLA-4, and LAG-3 in OVA tetramer-positive CD8 lymphocytes within the tumor on day 21 was analyzed using flow cytometry." (PMID 25354479, 2015). "Treatment with single agent anti-PD1 antibody also promoted 50% of tumor rejection while anti-LAG3 blockade treatment significantly delayed tumor growth as well when compared with the IgG control treatment." (PMID 26318293, 2015). "As for other NCRs, two other binding partners for LAG-3 have been described which are expressed in the tumor microenvironment: the Liver sinusoidal endothelial cell lectin (LSECtin) and Galectin-3 (Gal-3)." (PMID 26347741, 2015). "Preclinical studies have shown that combined treatment of LAG-3 and PD-1 blocking antibodies provided a synergistic anti-tumor effect." (PMID 25614821, 2015). "One interesting aspect of the current trial is that LAG-3 blockade will eventually be tested in combination with PD-1 blockade, a regimen that has demonstrated synergy in tumor, autoimmune, and infectious disease models." (PMID 25372844, 2014). "Dual targeting of PD-1 and TIM-3 or LAG-3 with mAbs synergistically enhanced anti-tumor responses and pre-clinical evaluations of a soluble Fc-LAG3 complex, which has now entered clinical development, were promising." (PMID 23935598, 2013). "Certain iRs (PD1, CTLA-4, TIM-3, LAG-3) can be particularly highly expressed in the tumor microenvironment (TILN), but there was high variability." (PMID 24391639, 2013).